XRCC1 (X-ray repair cross complementing 1)
Diseases named in the same sentence as XRCC1 in open-access papers (continued):
Sharing a sentence is not in itself a finding about the gene and the disease.
cervical carcinoma (continued). "The immunohistochemistry assay showed that XRCC1 protein expression levels were upregulated in cervical cancer patients with the XRCC1 rs3213245 CC genotype compared with the CT or TT genotypes." (PMID 29156789, 2017). "The genetic variants of the key components (i.e., HOGG1, XRCC1, ADPRT, and APE1) in the BER pathway and the risk of cervical cancer in the testing cohort were analyzed." (PMID 29156789, 2017). "We have demonstrated that SNPs of the XRCC1 gene at codon 399 influence the response of patients with locally advanced cervical carcinoma to platinum-based NAC." (PMID 19563645, 2009). "CpG-ODNs may mitigate cervical cancer RKI by blocking the activation of the PARP1/XRCC1 signaling axis, inhibiting DNA damage and oxidative stress response in renal tubule epithelial cells." (PMID 37773127, 2023). "It should be noted that the bioinformatics analysis conducted in the present study predicted that CpG-ODNs might regulate the downstream targets poly ADP-ribose) polymerase 1 (PARP1)/X-ray repair cross complementing 1 (XRCC1) in RKI in cervical cancer." (PMID 37773127, 2023). "To conclude, the present study provide evidence indicating that CpG-ODNs may attenuate RKI in cervical cancer by blocking PARP1/XRCC1 axis activation and inhibiting DNA damage and oxidative stress in renal tubular epithelial cells." (PMID 37773127, 2023). "Here, we found that the minor alleles of the XRCC1 gene significantly correlated to the cervical cancer group when compared to the negative group (OR = 3.43, 95% CI = 1.50–7.85, p = 0.00) or the elderly group (OR = 3.00, 95% CI = 1.26–7.10, p = 0.03)." (PMID 30616520, 2019). "In addition, the XRCC1 mRNA level of cervical cancer patients was determined to verify the transcriptional regulation of XRCC1 by the Sp1-Krox-20 complex in vivo." (PMID 29156789, 2017). "Our results showed that there was no obvious association between XRCC1 Arg194Trp or Arg280His and cervical cancer susceptibility." (PMID 27903984, 2017). "The meta-analysis of 16 studies found out that there were no obvious associations of XRCC1 Arg399Gln polymorphism with cervical cancer risk." (PMID 23675381, 2013). "SNP of XRCC1 gene at codon 399 influences the response of cervical carcinoma to platinum-based NAC." (PMID 19563645, 2009). "The fact that SNPs of XRCC1 at codon 399 influences response to NAC in locally advanced cervical carcinoma affirms previous results reported by the studies of other carcinomas, but the exact mechanism remains unknown." (PMID 19563645, 2009). "Similarly, our results also showed that the level of XRCC1 protein expression was significantly higher in patients with poor response than in those with good response to NAC in locally advanced cervical carcinoma." (PMID 19563645, 2009). "The role of genetic polymorphisms in key DNA repair genes such as XRCC1, XRCC2, and XRCC3, along with their respective SNPs, has been extensively studied for their association with cancer risk across different types of cancers, such as lung, breast, and cervical cancer." (PMID 38983993, 2024).
cervical carcinoma (continued). "Furthermore, the meta-regression of ethnicity showed no obvious difference (P > 0.05), implying that the ethnicity exerted no influence on the association between the XRCC1 Arg399Gln polymorphism and the risk of cervical cancer." (PMID 27903984, 2017). "However, whether the polymorphisms of the BER pathway components (i.e., HOGG1, XRCC1, ADPRT, and APE1) can affect the risk of cervical cancer remains unknown." (PMID 29156789, 2017). "To clarify the influence of the XRCC1 gene polymorphisms on the response to NAC, in the present study, we examined the association of the different genotypes (at codons 194 and 399), as well as protein expression with NAC response in patients with locally advanced cervical carcinoma." (PMID 19563645, 2009). "Bioinformatics analysis revealed that the downstream targets regulated by CpG-ODNs in cervical cancer RKI were primarily PARP1 and XRCC1." (PMID 37773127, 2023). "Herein, we set out to investigate the role of CpG-ODNs in RKI in cervical cancer and our results found that CpG-ODNs could inactivate the PARP1/XRCC1 axis to prevent RKI in cervical cancer." (PMID 37773127, 2023). "A recent study analyzed the expression of XRCC1, ERCC2, ERCC4 and ERCC1 in cervical tissue samples and showed that the levels of both mRNA and protein were lower in squamous intraepithelial lesions and cervical cancer samples than in samples from control patients." (PMID 30674977, 2019).
glioma (28 papers, 2012 to 2025). A benign or malignant brain and spinal cord tumor that arises from glial cells (astrocytes, oligodendrocytes, ependymal cells). "This comprehensive meta-analysis declared a significant association between ERCC2 rs13181, XRCC1 rs25487, and the risk of glioma." (PMID 39834980, 2024). "We identified 30 eligible studies investigating the PubMed records (up to January 2024) via a mishmash of the subsequent terms: brain tumors, glioma, glioblastoma, gene associations, SNPs, XRCC1, XRCC3, ERCC1, and ERCC2." (PMID 39834980, 2024). "In conclusion, the results of the present meta-analysis suggest that the XRCC1 Arg194Trp polymorphism is associated with increased risk of glioma, especially for Asians." (PMID 28423490, 2017). "Current evidence indicated that XRCC1 Arg194Trp polymorphism was associated with increased risk for glioma, especially in Asians; however, relevant studies involving other ethnic groups are required to validate our findings in further." (PMID 28423490, 2017). "The association between XRCC1 Arg194Trp polymorphism and glioma risk were inconsistent from published meta-analyses and epidemiological studies." (PMID 28423490, 2017). "From 2012 to 2016, there are 14 meta-analyses published to estimate the association between XRCC1 Arg194Trp polymorphism and glioma risk, but the results are contradictory." (PMID 28423490, 2017). "There was a potential decreased susceptibility to glioma in association with the XRCC1 Arg399Gln polymorphism, especially in Asians." (PMID 26249370, 2015). "Three extensively investigated polymorphisms (Arg399Gln, Arg194Trp, and Arg280His) in the X-ray repair cross-complementing group 1 (XRCC1) gene have been implicated in risk for glioma." (PMID 25375625, 2014). "At present, several systematic reviews and meta-analyses have been carried out as preliminary studies to determine the association between XRCC1 variants and glioma risk based on pervious published studies." (PMID 25375625, 2014). "Nevertheless, large-scale, well-designed and population-based studies are needed to further evaluate gene-gene and gene–environment interactions, as well as to measure the combined effects of these XRCC1 variants on glioma risk." (PMID 25375625, 2014). "The genetic effect of XRCC1 polymorphisms on glioma risk in Chinese populations remains largely inconclusive." (PMID 25375625, 2014). "Methodology: Meta-analyses assessing the association of XRCC1 Arg280His variation with glioma were conducted and subgroup analyses on ethnicity and source of controls were further performed." (PMID 24353504, 2013). "In order to avoid this issue, we performed a meta-analysis to provide the most comprehensive assessment of the association between XRCC1 polymorphisms and glioma risk." (PMID 23383237, 2013). "Individuals carrying the XRCC1 399A allele had an increased risk of glioma (OR = 1.33, 95% CI = 1.02–1.64)." (PMID 23385236, 2013). "In our meta-analysis, we accurately assessed the association between these XRCC1 polymorphisms and the risk of glioma and its histological subtypes by taking into account the effects of overlapping data." (PMID 23383237, 2013). "This meta-analysis was performed to derive a more precise estimation between XRCC1 polymorphisms (Arg399Gln, Arg194Trp, and Arg280His) and glioma risk." (PMID 23383237, 2013). "To date, many studies have investigated the associations between XRCC1 variants in DNA repair genes and the risk of glioma in different populations, but the results remain contradictory." (PMID 23383237, 2013). "Recent epidemiological studies suggest that Arg399Gln XRCC1 is associated with Parkinson’s disease, sporadic amyotrophic lateral sclerosis, and increased glioma risk." (PMID 23247283, 2012). "Meta-analyses assessing the association of the XRCC1 Arg194Trp variation with glioma were conducted and subgroup analyses based on ethnicity and source of controls were also performed." (PMID 23226774, 2012).
glioma (continued). "A systematic literature review and meta-analysis was conducted to explore the association between XRCC1 399 G → A and glioma." (PMID 23101479, 2012). "Moreover, XRCC1 Arg194Trp and XRCC1 Arg399Gln were revealed to be strongly associated with susceptibility to glioma among the Chinese population according to a large case-control study." (PMID 38217545, 2024). "It has been previously reported that the rs25489 (Arg280His) and Arg399Gln (rs25487) polymorphisms of the XRCC1 gene may affect the risk of developing glioma in the Chinese population." (PMID 31528233, 2019). "In addition, recent work has suggested that downregulation of RAP1 and XRCC1 licenses IDH1-mutant glioma cells to engage the ALT mechanism after ATRX loss." (PMID 30226859, 2018). "Finally, this meta-analysis merely detected the association between the XRCC1 Arg194Trp polymorphism and glioma based on crude data." (PMID 28423490, 2017). "These polymorphisms, which involve amino acid changes at evolutionarily conserved sequences, could alter the function of XRCC1, which may diminish repair kinetics in individuals with the variant alleles and increase the risk of glioma in humans." (PMID 25375625, 2014). "A meta-analysis of 11 case-control studies with 2,808 glioma cases and 3,114 control subjects identified that the XRCC1 Arg399Gln polymorphism may contribute to the susceptibility to gliomas in Asian individuals." (PMID 25013509, 2014). "Therefore, in the present study, we performed a meta-analysis to elucidate the relationship between XRCC1 polymorphisms and glioma risk in Chinese populations by combining all available studies." (PMID 25375625, 2014). "For the overall data, XRCC1 Arg280His polymorphism has little association with glioma risk." (PMID 24353504, 2013). "The observation that conditional neuron disruption of Xrcc1 in mice influences neuronal development and causes accumulation of DNA strand breaks makes it plausible that XRCC1 variants might contribute to neurodegenerative diseases and influence glioma risk." (PMID 23247283, 2012). "Research on gliomas has found that emodin can induce apoptosis within 48 hours, but resistance develops after 48 hours, potentially due to the high expression of XRCC1 in glioma cells." (PMID 39346898, 2024). "Intriguingly, gliomas exhibit reduced XRCC1 expression compared to normal tissues and augmented XRCC1 expression significantly impedes malignant biological behaviors." (PMID 38217545, 2024). "We conducted a comprehensive meta-analysis to investigate the ERCC1 (rs3212986), ERCC2 (rs13181), XRCC1 (rs25487), and XRCC3 (rs861539) genes to see if they are any risk factors for glioma susceptibility." (PMID 39834980, 2024). "Our meta-analysis included 30 articles and thus constituted a wide-ranging evaluation of the relationships of ERCC1 C8092A, ERCC2 Lys751Gln, XRCC1 Arg399Gly, and XRCC3 T241M polymorphisms with the risk of glioma in various populations." (PMID 39834980, 2024). "We collected eligible studies together to evaluate the association between ERCC1, ERCC2, XRCC1, and XRCC3 polymorphisms and glioma risk in the present study." (PMID 39834980, 2024). "We conducted a comprehensive meta-analysis with the aim of investigating the ERCC1 (rs3212986), ERCC2 (rs13181), XRCC1 (rs25487), and XRCC3 (rs861539) genes to see if there are any risk factors for glioma susceptibility." (PMID 39834980, 2024). "Variations in genes involved in DNA repair, cell cycle, metabolism, and inflammation pathways have been recognized as a key basis of inherited glioma susceptibility, such as PRKDC, XRCC1, PARP1, ERCC1, ERCC2, EGF, and IL13." (PMID 36733406, 2023). "Hence, it is still unclear whether XRCC1 Arg194Trp polymorphism is associated with risk of glioma." (PMID 28423490, 2017). "For instance, carriers of both XRCC1 Gln399Gln and XRCC3 Met241Met were associated with a three-fold increased risk of glioma." (PMID 23383237, 2013).
glioma (continued). "Further analysis of the interactions of two susceptibility-associated SNPs, XRCC1 Arg194Trp and XRCC3 Thr241Met, showed that the combination of the XRCC1 194T and XRCC3 241T alleles brought a large increase in glioma risk (OR = 2.75, 95% CI = 1.54–4.04)." (PMID 23385236, 2013). "Distribution of XRCC1 Arg280His genotypes among glioma cases and controls included in the meta-analysis." (PMID 24353504, 2013). "XRCC1 Arg194Trp, XRCC1 Arg399Gln, and XRCC3 C241T, appear to be associated with susceptibility to glioma in a Chinese population." (PMID 23385236, 2013). "A systematic literature review and meta-analysis of six case-control studies with 2,362 glioma cases and 3,085 control subjects did not indicate a major role of the XRCC1 Arg399Gln polymorphism in influencing the risk of glioma among Caucasian individuals." (PMID 25013509, 2014). "In summary, the data of the present meta-analysis failed to suggest an association between XRCC1 Arg280His polymorphism and glioma risk." (PMID 24353504, 2013). "Despite the biologic plausibility of an association between XRCC1 399 G → A and risk of glioma, this meta-analysis does not provide evidence of such an association." (PMID 23101479, 2012). "In conclusion, the results of the present meta-analysis failed to suggest an association of the XRCC1 Arg194Trp polymorphism with glioma risk." (PMID 23226774, 2012). "This meta-analysis does not suggest a major role of the XRCC1 399 G → A polymorphism in influencing risk of glioma among Caucasians." (PMID 23101479, 2012). "In conclusion, the results of the present study failed to suggest an association between the XRCC1 Arg194Trp polymorphism and glioma risk." (PMID 23226774, 2012). "Thus, a screening test that will include the ERCC1 (rs3212986), ERCC2 (rs13181), XRCC1 (rs25487), and XRCC3 (rs861539) genes may well be helpful for the prevention and earliest treatment of patients with glioma susceptibility." (PMID 39834980, 2024). "However, Zhang L et al13 meta study failed to suggest that XRCC1 Arg280His polymorphism is associated with glioma risk." (PMID 37250582, 2023). "In the end, our meta-analysis of 16 case-control studies indicated that XRCC1 Arg194Trp polymorphism probably was associated with increased risk of glioma, and the cumulative analysis suggested that the non-significant association would be change to significant if the sample sizes were enough." (PMID 28423490, 2017). "Work indicates that the Arg399Gln polymorphism in the XRCC1 DNA repair gene may contribute to the likelihood of developing glioma in Asian patients but not in Caucasians." (PMID 27135830, 2016). "Among them, the majority were excluded after the first screening based on abstracts or titles, mainly because they were overlapped citations, not relevant to the XRCC1 polymorphisms and glioma risk, reviews, conference abstracts, or not a related gene polymorphism." (PMID 25375625, 2014).